PAX8 (paired box 8)
Description:
Transcription factor for the thyroid-specific expression of the genes exclusively expressed in the thyroid cell type, maintaining the functional differentiation of such cells.
Synonyms: PAX-8
Tractability: PROTAC: a small molecule that binds it is known.
Target class: Transcription factor
Gene: Protein-coding gene on chromosome 2 (113,215,997 to 113,278,921, reverse strand). Ensembl gene ENSG00000125618.
Subcellular location: Nucleus
Subcellular location (Human Protein Atlas): Nucleoplasm
Pathways (Reactome):
Developmental Biology: Formation of intermediate mesoderm; Formation of the nephric duct
Gene Ontology:
Molecular function: DNA binding; DNA-binding transcription factor activity; protein binding; RNA polymerase II cis-regulatory region sequence-specific DNA binding; sequence-specific double-stranded DNA binding; transcription cis-regulatory region binding; DNA-binding transcription factor activity, RNA polymerase II-specific; thyroid-stimulating hormone receptor activity
Biological process: branching involved in ureteric bud morphogenesis; cellular response to gonadotropin stimulus; central nervous system development; DNA-templated transcription; kidney development; mesenchymal to epithelial transition involved in metanephros morphogenesis; metanephric comma-shaped body morphogenesis; metanephric epithelium development; metanephric S-shaped body morphogenesis; otic vesicle development; positive regulation of DNA-templated transcription; positive regulation of thyroid hormone generation; positive regulation of transcription by RNA polymerase II; regulation of thyroid-stimulating hormone secretion; thyroid gland development; anatomical structure morphogenesis; inner ear morphogenesis; mesonephros development; metanephric collecting duct development; metanephric distal convoluted tubule development; metanephric nephron tubule development; metanephric nephron tubule formation; metanephros development; nervous system development; positive regulation of mesenchymal to epithelial transition involved in metanephros morphogenesis; and 16 more
Cellular component: nucleoplasm; nucleus; chromatin
Genetic constraint (gnomAD): Loss-of-function variants: 12 observed, 46.85 expected, observed/expected ratio (o/e) 0.26, 90% interval 0.16 to 0.41. The upper end of that interval is the gene's LOEUF score, 0.41, which puts it in group 1 of 6, group 1 being the genes least tolerant of losing a copy. Missense variants: 526 observed, 567.72 expected, observed/expected ratio (o/e) 0.93, 90% interval 0.86 to 1. Synonymous variants: 272 observed, 236.09 expected, observed/expected ratio (o/e) 1.15, 90% interval 1.04 to 1.27.
Cancer hallmarks: escaping programmed cell death (promotes); proliferative signalling (promotes); invasion and metastasis (promotes)
Homologues: Orthologues: chimpanzee PAX8 (100% identical), macaque PAX8 (99% identical), guinea pig PAX8 (99% identical), mouse Pax8 (98% identical), rat Pax8 (98% identical), dog PAX8 (92% identical), tropical clawed frog pax8 (77% identical), rabbit PAX8 (71% identical), zebrafish pax8 (67% identical). Paralogues in human: PAX2 (54% identical), PAX5 (51% identical), PAX7 (34% identical), PAX3 (32% identical), PAX1 (30% identical), PAX9 (30% identical), PAX4 (23% identical), PAX6 (15% identical), NOBOX (11% identical), ARX (10% identical), EVX2 (10% identical), VSX2 (10% identical), and 38 more.
Diseases named in the same sentence as PAX8 in open-access papers:
PAX8 is named in the same sentence as 292 diseases in open-access papers, as found by Europe PMC text mining. Sharing a sentence is not in itself a finding about the gene and the disease. The quoted sentences say what the papers report.
thyroid cancer (113 papers, 2005 to 2026). "Renal and thyroid carcinomas are the diagnostic traps on the basis of PAX8 expression and require additional markers for final classification in metastatic workups." (PMID 41664069, 2026). "Regarding PAX8, loss of its expression is more typical of poorly differentiated thyroid cancers, and ATC has been observed to have loss or discontinuous patterns of E-cadherin expression." (PMID 39744583, 2025). "A chromosomal rearrangement found in thyroid carcinoma is that between the genes PAX8 and PPARγ, PAX8 encodes a transcription factor that is essential for normal thyroid development." (PMID 28117295, 2017). "The paired box 8 (PAX8)–peroxisome proliferator-activated receptor-γ (PPARγ) fusion gene (PAX8/PPARγ) is another prominent recombinant oncogene in thyroid cancer, occurring in up to 60% of FTC and follicular variant PTC (FVPTC)." (PMID 26886957, 2016). "Many studies have examined use of other molecular markers including RAS, RET/PTC rearrangement, and/or PAX8/PPARγ rearrangement to improve the diagnostic accuracy of thyroid carcinomas." (PMID 23049733, 2012). "Furthermore, the METTL3‒PAX8‒YTHDC1 axis is linked to thyroid cancer dedifferentiation and progression, positioning it as a potential target for PTC treatment." (PMID 40819127, 2025). "In summary, the expression pattern of β-catenin and loss of expression of PAX8 and E-cadherin are useful for detecting poorly differentiated thyroid carcinoma subtypes such as ATC; therefore, their use in an immunohistochemical panel is recommended for a more comprehensive diagnosis of ATC." (PMID 39744583, 2025). "DICER1 silencing decreased PAX8 expression and, importantly, the expression and activity of the sodium iodide symporter, which is essential for the diagnostic and therapeutic use of radioiodine in thyroid cancer." (PMID 33176626, 2021). "Likewise, BRAFV600E mutated as well as wild type thyroid cancer cells demonstrated relatively low expression of NIS as well as PAX8 (direct regulator of NIS) compared to normal cells." (PMID 30760304, 2019). "BRAF mutation, RAS mutation, RET/PTC rearrangement, PAX8/PPARγ rearrangement, and TERT promoter mutation, are among the major molecular indicators linked to thyroid cancer." (PMID 38501105, 2024). "A particular genetic change that is present in follicular thyroid carcinoma (FTC) and helps distinguish this thyroid cancer subtype from other types of thyroid cancer is the PAX8-PPARγ rearrangement." (PMID 38501105, 2024). "Significantly, the down-regulate of PAX8 can reverse the inhibitory effect of METTL3 on the proliferative ability of thyroid cancer." (PMID 38993572, 2024). "Most thyroid cancers contain one of several known driver mutations, such as the V600E substitution in BRAF, RAS mutation, RET gene fusion, or PAX8/PPARγ gene fusion." (PMID 38791384, 2024). "The overall differences and similarities between PAX8 target genes in thyroid development, adult thyroids, and thyroid cancers remain to be shown." (PMID 35806410, 2022). "The literature reported that nevirapine induced redifferentiation and RAI uptake via the TSHR/cAMP/CREB/PAX8 signal pathway in dedifferentiated thyroid cancer." (PMID 36142613, 2022). "Well differentiated thyroid cancers almost universally express the markers thyroid transcription factor-1 (TTF-1), PAX8, thyroglobulin and B-catenin; however, loss of expression of these proteins is often characteristic of ATC." (PMID 35193694, 2022).
thyroid cancer (continued). "TTF1 and PAX8 are both markers of embryonic thyroid development that are often co-expressed in thyroid cancer cells, and TTF1 was shown to regulate the expression of PAX8 in thyroid cancer cells." (PMID 35806410, 2022). "Paired box gene 8 (PAX-8) retains expression in de-differentiated thyroid cancers and helps differentiate them from other head and neck neoplasms that are not separated due to poorly differentiated histomorphology." (PMID 35154933, 2022). "Pioglitazone is an insulin sensitizer for type 2 diabetes with therapeutic effects in mouse models of thyroid cancer due to the fusion protein (PAX8-PPARg) present in 30% of thyroid cancer." (PMID 35327549, 2022). "This lncRNA targets two upregulated miRNAs in thyroid cancer, miR-182-5p and miR-20a-5p, which silence essential players of thyroid differentiation and apoptosis including PAX8 and BCL247." (PMID 35562181, 2022). "Evaluation of thyroid FNAs with the Unified Assay identified all fusion proteins described for thyroid cancer in TCGA, the most common fusion pair being PAX8-PPARg, with other common fusion partners including RET, NTRK1/3, ALK, and BRAF." (PMID 36675685, 2022). "PAX8 protein is positive in thyroid carcinoma, renal cell carcinoma, Mullerian tumours (female genital tract), and thymic tumours." (PMID 35328664, 2022). "Some studies have indicated that the expression of PPARγ is reduced in thyroid cancer while others revealed the normal expression of PPARγ or the inactivation of PPARγ by the Pax-8-PPAR-γ fusion protein (PPFP)." (PMID 34557159, 2021). "We have previously reported that both TG and TPO mRNA and protein are re-expressed in dedifferentiated thyroid cancer cells (NKX2-1−/PAX8+) infected with adenoviral vectors containing Nkx2-1 (AdNKX2-1), which induces radioiodide organification and retention." (PMID 34748583, 2021). "In thyroid cancer, main driver genetic alterations include BRAF (V600E) and RAS (NRAS involving codons 12 and 61) mutations, RET gene fusions, and PAX8-PPARG gene fusions." (PMID 34680260, 2021). "Several studies have reported the impaired expression of thyroid transcription factors such as NKX2-1 and PAX8 in thyroid carcinomas, suggesting that their deregulation is pivotal for the initiation and progression of thyroid neoplasms." (PMID 33176626, 2021). "FTC is a less common subtype of WDTC with 10–15% cases of all the thyroid carcinomas, driven by RAS, BRAFV600E mutations, and PAX8/PPARγ (Paired Box Gene 8/Peroxisome Proliferator-Activated Receptor Gamma) rearrangements." (PMID 35008887, 2021). "Among the significantly regulated genes from the KEGG-derived THS pathway, only PAX8 (−1.94x) was previously related to the thyroid cancer, albeit to the follicular form." (PMID 32887258, 2020). "Current diagnostic biomarkers in thyroid cancer include point mutations in the BRAF, NRAS, KRAS, HRAS genes, and rearrangements in paired box 8 (PAX8)/peroxisome proliferator-activated receptor gamma (PPARG) and RET." (PMID 33158279, 2020). "A molecular test was devised using real-time PCR to detect common genetic alterations in thyroid cancer, including BRAF, N-, H-, and K-RAS mutations and rearrangements of RET/PTC and PAX8/PPARr." (PMID 32781560, 2020). "IHC analysis demonstrates that the solid structures observed by H&E staining in FOXE1+/+ thyroid cancers are composed of PAX8- and TG-positive cell nests distributed throughout the gland." (PMID 33375029, 2020). "BRAF-targeted paired box gene-8 (PAX8), a thyroid-specific transcription factor, generally dysregulated in BRAF-mutated thyroid cancer." (PMID 30760304, 2019). "ATC lacks most markers seen in thyroid cancer such as thyroglobulin, TTF1, NIS, and TSHR, except PAX8 that can be present consistently in squamous variant ATC but in only 50% of ATC with spindle cell features." (PMID 31835496, 2019).
thyroid cancer (continued). "The low levels of TTF-1 and loss of its nuclear localization in thyroid cancer have been associated with dedifferentiation and increased malignancy, whereas the role of PAX8 in thyroid cancer is still controversial." (PMID 31750236, 2019). "We also show that PAX8 modulated NIS expression in thyroid cancer after LDR exposure in thyroid cells." (PMID 30760304, 2019). "The present findings provide evidence that LDR-induced PAX8 acts as an important regulator for suppression of thyroid carcinogenesis through novel STAT3/miR-330-5p pathway in thyroid cancers." (PMID 30760304, 2019). "To confirm miRNAs identified by prediction tools, we checked further PAX8 levels in 850-5C thyroid carcinoma cells after miR-144-3p and miR-330-5p inhibitor treatment." (PMID 30760304, 2019). "A small portion of thyroid carcinomas carries an oncogenic paired box 8 (PAX8) and PPARγ fusion protein." (PMID 31614690, 2019). "PAX8 is a nuclear marker, usually expressed in Müllerian tumours (ovarian and endometrial), renal cell carcinomas and thyroid carcinomas of follicular cell origin." (PMID 29621151, 2018). "Overall, PAX8 is a specific and sensitive marker for Müllerian tumours, renal cell, ovarian and thyroid carcinomas." (PMID 29621151, 2018). "Several findings indicate that expression of the thyroid-specific transcription factor PAX8 is reduced in thyroid cancer." (PMID 27249794, 2016). "We also show that the downregulation of NRP2 mediated by PAX8 reduces cell proliferation and suppresses cell migration and invasion of thyroid cancer cells." (PMID 26030152, 2015). "To investigate the role of NRP2 in thyroid cancer, we have chosen the FB-2 cell line and selected stable cell clones overexpressing PAX8." (PMID 26030152, 2015). "A chromosomal translocation results in production of an oncogenic PAX8-PPARG fusion protein (PPFP) in thyroid carcinomas." (PMID 26595524, 2015). "The majority of thyroid carcinomas contain one of a small number of driver mutations, such as BRAF or RAS mutations, gene fusions involving RET, or gene fusions between PAX8 and PPARG." (PMID 26595524, 2015). "In another study with a large tumour panel, PAX8-positive tumours were frequently detected in renal cell carcinomas (90%), thyroid cancers (90%), endometrial cancers (84%), cervical adenocarcinomas (83%), and ovarian cancers (79%)." (PMID 24602166, 2014). "Here, we show that in human thyroid cancer cell lines, Wnt4 and PAX8 mRNA levels are strongly reduced." (PMID 25270402, 2014). "Alterations of PPARG have been discovered in a large number of thyroid cancer samples, such as PAX8/PPARG fusion oncogene in follicular thyroid carcinoma and PTCs, and another PPARG agonist (RS54444) in ATCs." (PMID 24718460, 2014). "Chromosomal translocations involving PAX5 and PAX8 genes in thyroid cancer indicate that PAX genes have an oncogenic capacity when constitutively expressed, either as part of a fusion gene or as a whole gene." (PMID 23425942, 2013). "There have been several genetic abnormalities associated with thyroid carcinoma including point mutations such as those in the RAS and BRAF genes, and chromosomal rearrangements such as RET/PTC and PAX8/PPARγ." (PMID 23717622, 2013). "The results obtained suggest that Pax8 regulates several pathways, mainly involved in the regulation of cell cycle, thyroid cancer and apoptosis, thus confirming that Pax8 is a master regulatory gene." (PMID 21966443, 2011). "Regarding specific mutations that constituted the panel for thyroid cancer diagnostic, RAS, BRAF, RET/PTC, and PAX8/PPARγ mutations had all a 100% positive predictive value for cancer." (PMID 22654559, 2011). "Real-time PCR showed that HNF3β/FoxA2, TTF-1, and Pax-8 were expressed in normal thyroid tissue; in contrast, levels were either very low or undetectable in thyroid carcinoma cell lines." (PMID 18682709, 2008). "Pax8 is expressed in approximately 80% of mesenchymal thyroid cancer cases." (PMID 40400806, 2025).
thyroid cancer (continued). "Collectively, these findings support the hypothesis that PAX8-PPARγ contributes to thyroid cancer cell survival and proliferation, highlighting its potential as a therapeutic target." (PMID 40506992, 2025). "For instance, thyroid carcinoma, esophageal carcinoma, and germ cell tumors express PAX8." (PMID 40506992, 2025). "The PAX8/PPARγ rearrangement is a molecular abnormality found in thyroid carcinoma, especially FTC." (PMID 38501105, 2024). "Klhl14AS has already been described as ceRNA in thyroid cancer, where it acts as a decoy for miRNA182-5p and miRNA20a-5p, reducing their binding to the transcripts of both Pax8, a master regulator of thyroid differentiation, and Bcl2, a survival-promoting gene essential in thyroid physiology." (PMID 37238229, 2023). "Esophageal cancer patients with high expression of FOXN1, GRHL3, and HES2, stomach cancer patients with high expression of ONECUT2, thyroid cancer patients with high expression of PAX8, and uterine cancer patients that expressed elevated levels of MECOM had decreased survival." (PMID 37627195, 2023). "Discusses the Pax-8-PPAR-γ fusion protein in thyroid carcinoma." (PMID 38074042, 2023). "Thus, the combination of Napsin A (positive in lung carcinoma) and monoclonal PAX8 (positive in thyroid carcinoma) has been suggested as the best panel of markers to distinguish between primary thyroid carcinomas and metastatic lung carcinomas to thyroid." (PMID 35328664, 2022). "Intriguingly, while driver gene fusions (RET fusions or NTRK fusions in PTCs, PAX8-PPARγ fusions in FTCs) are often mutually exclusive with driver gene mutations in well-differentiated thyroid cancer, they are generally absent in ATCs." (PMID 34944959, 2021). "Among the three compounds, it has been reported that pioglitazone may be the potential drug in patients with PAX8-PPARγfusion protein (PPFP) thyroid cancer and thyroid cancer." (PMID 34721037, 2021). "Pax8 expression is also frequently observed in renal, bladder, ovarian, and thyroid cancer cells." (PMID 34195082, 2021). "Despite the well-established role of the PAX8-PPARγ fusion oncogene, the expression landscape of experimentally validated PPARγ target genes remains unclear in thyroid carcinoma." (PMID 34680260, 2021). "Thus, PAX8 played an important role in raising radioactivity in differentiated thyroid cancer cells by nevirapine." (PMID 32300552, 2020). "Unlike other driver mutations in thyroid cancers that overexpress kinase signaling pathways, PAX8-PPARG gene fusion involves tumor immunology and several cancer-related pathways such as apoptosis, cell cycle, and motility." (PMID 31835496, 2019). "Similarly, PAX8 overexpression enhances the migration and tumorigenicity of thyroid carcinoma cells." (PMID 30021604, 2018). "PAX8 is a thyroid-specific transcription factor whose expression is dysregulated in thyroid cancer." (PMID 27249794, 2016). "Extensive work has been done to characterize PAX8’s role in thyroid carcinomas." (PMID 27249794, 2016). "POU5F1 and PAX8 are homeobox-containing transcription factors, a family of genes that play a role in cell fate and differentiation programs, and whose role in cancer is well recognized, particularly PAX8 in thyroid cancer." (PMID 26684754, 2015). "We identified and replicated an interaction between variants in PAX8 and STK17B, suggesting they may be new players in thyroid cancer susceptibility." (PMID 24086368, 2013). "In addition to identifying a potential role of TSHR variants in cPTC risk, we have detected and independently replicated for the first time an epistatic relationship between the PAX8 and STK17B genes in thyroid cancer susceptibility." (PMID 24086368, 2013). "PAX8 expression has also been identified in thyroid carcinomas." (PMID 23425942, 2013).